MBD3L2B (methyl-CpG binding domain protein 3 like 2B)
Gene: Protein-coding gene on chromosome 19 (7,018,969 to 7,021,431, reverse strand). Ensembl gene ENSG00000196589.
Subcellular location (Human Protein Atlas): Nucleoli; Nucleoplasm; Cytosol
Gene Ontology:
Molecular function: methyl-CpG binding
Biological process: DNA methylation-dependent constitutive heterochromatin formation; negative regulation of transcription by RNA polymerase II
Cellular component: nucleus
Homologues: Orthologues: rat Mbd3l2 (43% identical), rat Mbd3l3 (40% identical), mouse Mbd3l2 (40% identical), zebrafish mbd3a (32% identical), tropical clawed frog mbd3 (31% identical), Drosophila melanogaster MBD-like (23% identical). Paralogues in human: MBD3L2 (100% identical), MBD3L3 (99% identical), MBD3L4 (99% identical), MBD3L5 (99% identical), MBD3L1 (36% identical), MBD2 (32% identical), MBD3 (32% identical), MBD1 (22% identical).